DUSP6 (dual specificity phosphatase 6)
Diseases named in the same sentence as DUSP6 in open-access papers (continued):
Sharing a sentence is not in itself a finding about the gene and the disease.
breast carcinoma (28 papers, 2005 to 2025). "From this analysis, we identified genes such as CITED2 and DUSP6 that are previously implicated in breast cancer metastasis." (PMID 37117180, 2023). "Overexpression of DUSP6 causes estrogen receptor-positive breast cancer cells to become resistant to the growth inhibitory effects of tamoxifen." (PMID 24260056, 2013). "DUSP6 expression also selectively associated with poor patient survival in HER2+ breast cancers." (PMID 38886591, 2024). "Given that DUSP6 overexpression in breast cancer has been linked to resistance to tamoxifen therapy, we postulate that HER2-mediated resistance to hormone therapies may be in part due to increased DUSP6 expression." (PMID 26859151, 2016). "In addition to their potential role in immune regulation, studies have discussed the association of DUSPs namely DUSP1, DUSP4 and DUSP6 in oncogenesis especially in the epithelial-to-mesenchymal transition of breast cancer cells and the maintenance of cancer stem cells." (PMID 31035605, 2019). "For example, the expression of HSPA1A contributes to radioresistance in breast cancer and DUSP6 regulates radiosensitivity in GB and esophageal squamous cell carcinoma." (PMID 39417309, 2025). "Conversely, other studies reported that DUSP6 overexpression fosters colony formation and migration in breast cancer 38 and glioblastoma cells 10, highlighting the nuanced and context-dependent nature of the role of DUSP6 in cancer." (PMID 41210685, 2025). "Most of these genes were associated with cancers of metabolic systems (DUSP6, SGK1, BMP4, RASGRF1, GDF15) followed by breast cancer (CACNA2D3, ITGB7), cancers of the central nervous system (PRKCA), or leukemia (MECOM, JAK3)." (PMID 36624125, 2023). "While DUSP6 induces proliferation in breast cancer, lung cancer, and thyroid carcinoma, DUSP6 inhibits proliferation and suppresses tumor progression in pancreatic, ovarian, and non-small lung cancer." (PMID 38138967, 2023). "Activation of oncogenic RAS or the TGF-β signaling in breast cancer cells stimulates ΔNp63 transcriptional activity and then induces the transcription of the dual-specificity phosphatase 6 (DUSP6) gene, whose expression is mainly restricted to stem cells." (PMID 37848625, 2023). "DUSP6 is a dual-specificity phosphatase (DUSP) involved in breast cancer progression, recurrence, and metastasis." (PMID 31238530, 2019). "Inhibition of DUSP1 and DUSP6 induces apoptosis of highly aggressive breast cancer cells through the increased activation of MAPK signaling." (PMID 31035605, 2019). "This suggests a potential role for DUSP6 to mediate active gene transcription programs in CTCs from metastatic breast cancer patients." (PMID 31238530, 2019). "High DUSP6 expression was found to be associated with poor survival in ALL and breast cancer patients." (PMID 31235852, 2019). "We also examined DUSP6 expression in surviving tumor cells in a mouse model of breast cancer metastasis treated with Abraxane or anti-PD1." (PMID 31238530, 2019). "DUSP6 is predominately expressed in the cytoplasm of breast cancer cells such as the commonly used cell lines MCF-7 and MDA-MB-231." (PMID 31238530, 2019). "In breast cancer the suppression of DUSP6 leads to reduced cell proliferation and results in G0/G1 arrest." (PMID 28714904, 2017). "Publicly available HER2-positive breast cancer datasets also confirmed DUSP6 overexpression, suggesting a specific involvement of DUSP6 in breast cancer." (PMID 29100381, 2017). "Consistent with earlier reports, we found that DUSP6 is upregulated in HER2+ breast carcinomas in comparison to normal mammary tissue." (PMID 26859151, 2016). "Little is known about DUSP6 expression in breast cancer tissue, except that DUSP6 is upregulated in HER2+ breast carcinomas." (PMID 26859151, 2016). "Interestingly, DUSP6 was the only one of these four phosphatases that was selectively overexpressed in the target HER2+ subtype of breast cancers." (PMID 38886591, 2024).
breast carcinoma (continued). "As a result, DUSP6 empowers ΔNp63 and promotes metastatic behaviors in breast cancer cells." (PMID 37848625, 2023). "In 19 out of 21 patients TNBC metastatic breast cancer patient brain metastases, DUSP6 had nuclear expression, suggesting that the brain metastasis may form from CTCs via a nuclear DUSP6-dependent pathway." (PMID 31238530, 2019). "Several DUSPs are implicated in breast cancer metastasis, for example, DUSP1, DUSP4, and DUSP6." (PMID 31238530, 2019). "DUSP6 is predominantly cytoplasmic in HER2+ primary breast cancer cells, but the expression and subcellular localization of DUSPs, especially DUSP6, in HER2-positive circulating tumor cells (CTCs) is unknown." (PMID 31238530, 2019). "Third, the nuclear distribution of DUSP6 in CTCs and brain metastases may be prognostic, the majority of metastatic breast cancer patients with brain metastases had cancer cells positive for DUSP6 and all CTCs examined were also DUSP6 positive." (PMID 31238530, 2019). "DUSP6 is enriched in HER2-positive breast cancer tumor, the overexpression of which confers resistance to tamoxifen endocrine therapy, and we previously showed that DUSP6 knockdown by RNA interference increased CSC formation but inhibited cell proliferation in TNBC cell lines in vitro." (PMID 31238530, 2019). "DUSP6 expression has been reported to play an oncogenic role in breast cancers." (PMID 30517191, 2018). "In breast, DUSP4 acts also on ERK1/2 along with a breast cancer-related protein, DUSP6." (PMID 28603644, 2017). "Moreover, DUSP6 is overexpressed in patient-derived HER2+ breast carcinomas compared to benign mammary tissue." (PMID 26859151, 2016). "Furthermore, ER-/PR-/HER2+ breast cancers showed weak to moderate cytoplasmic DUSP6 expression, with up to 10% of cells showing weak nuclear staining." (PMID 26859151, 2016). "DUSP6 IHC analyses were conducted in benign and a number of malignant breast cancer tissues." (PMID 26859151, 2016). "DUSP6 is upregulated in myeloma, melanoma, glioma, glioblastoma, keratinocytes and breast cancer." (PMID 24260056, 2013). "Furthermore, DUSP6 increases resistance to tamoxifen treatment in breast cancer." (PMID 41210685, 2025). "Interestingly, DUSP6 is involved in maintaining the mesenchymal state in breast cancer." (PMID 32771050, 2020). "To understand whether nuclear DUSP6 is associated with drug resistance, we next examined DUSP6 expression in the 4T1 TNBC metastatic mouse breast cancer model treated with control vehicle, Abraxane (nab-paclitaxel, 30 mg/kg), or anti-PD1 (RMP1–14, 10 mg/kg) using the ASI digital pathology system." (PMID 31238530, 2019). "DUSPs such as DUSP1, DUSP4, and DUSP6 are involved in EMT and breast cancer stem cell (CSC) activity regulation." (PMID 41158869, 2025). "Together with its role as breast cancer oncogene involved in therapy resistance, these data imply FOXM1 as a viable candidate inducing DUSP6 expression during the DTP-DTEP transition." (PMID 38886591, 2024). "After discovering the role for DUSP6 in the development of HER2i tolerance, we wanted to address its role in HER2+ breast cancer cells with stable HER2i resistance." (PMID 38886591, 2024). "DUSP6 is a member of the MAPK phosphatase family which plays a pro-oncogenic role in human glioblastoma, thyroid carcinoma, breast cancer, and acute myeloid carcinoma via the MAPK signaling pathway." (PMID 34490085, 2021). "Our microscopy and immunohistochemistry analyses reveal a strong cytoplasmic bias for DUSP6 during EMT and in both normal and malignant breast cancer tissues." (PMID 26859151, 2016). "Several DUSP family members are thought to be involved in breast cancer metastasis including DUSP1, DUSP4, and DUSP6." (PMID 26859151, 2016). "Here we show that DUSP1, DUSP4, and DUSP6 are involved in epithelial-to-mesenchymal transition (EMT) and breast cancer stem cell (CSC) regulation." (PMID 26859151, 2016).
breast carcinoma (continued). "DUSP1, DUSP4, and DUSP6 were constitutively expressed in both epithelial MCF-7 and mesenchymal MDA-MB-231 breast cancer cell lines." (PMID 26859151, 2016). "Expression levels of BDNF and BDNF-correlated genes CCND2, DUSP6, EGR1, KLF10 and PTPRF are altered in breast cancer." (PMID 19737418, 2009). "The pattern of retinoid responsiveness for six of 13 target genes (RARβ2, CYP26A1, CRBP1, RGS16, DUSP6, EGR1) correlated with phenotypic retinoid sensitivity, across a panel of retinoid-sensitive or -resistant lung and breast cancer cell lines." (PMID 16012519, 2005). "Similarly, DUSP6 impaired cell migration in esophageal squamous cell and nasopharyngeal carcinoma, but oppositely, it increased cell migration in an MDA-MB-231 breast cancer cell line and gastric cancer." (PMID 40362381, 2025). "Linking our results further to future therapy of HER2+ brain metastasis, we showed that DUSP6 knockdown increases sensitivity to tucatinib+trastuzumab+capecitabine combination regimen, which show significant clinical activity in HER2+ breast cancer patients with brain metastasis." (PMID 38886591, 2024). "We report for the first time that nuclear DUSP6 was present in CTCs from metastatic breast cancer patients regardless of CTC HER2 status." (PMID 31238530, 2019). "DUSP6 is also upregulated in the cytoplasm of primary malignant breast cancer cells in HER2-positive breast cancer patients regardless of estrogen receptor/progesterone receptor (ER/PR) status." (PMID 31238530, 2019). "Since DUSP6 directly dephosphorylates ERK1/ERK2, we reasoned that DUSP6 may participate in HER2-positive CTCs in metastatic breast cancer patients." (PMID 31238530, 2019). "We previously showed that DUSP6 was exclusively cytoplasmic in primary HER2+ER−PR− breast cancers from metastatic breast cancer patients, with no nuclear DUSP6 expression in primary TNBCs." (PMID 31238530, 2019). "Taken together, these data suggest that DUSP6 is upregulated in malignant HER2+ breast cancers, regardless of ER/PR status." (PMID 26859151, 2016). "Knockdown of DUSP1, DUSP4, and DUSP6 involved in the formation of CD44hi/CD24lo/EpCAM+ breast CSCs, and importantly DUSP1 knockdown reduces CSC formation, while DUSP4 and DUSP6 knockdown enhance CSC formation, suggesting that DUSPs modulate EMT and CSC regulation in breast cancer differentially." (PMID 41158869, 2025). "The dual-specificity phosphatase 6 (DUSP6, MKP3) is a negative feedback regulator of the extracellular signal-regulated kinase (ERK) pathway and its expression has been associated with metastasis in breast cancer." (PMID 41149583, 2025). "However, DUSP6 mRNA expression was neither a prognostic factor in Luminal B or Basal subtypes, nor across unselected breast cancer patient population, further highlighting the selective connection between DUSP6 and HER2 in breast cancer progression." (PMID 38886591, 2024). "Clinical relevance of DUSP6 in HER2+ breast cancers among the four candidate phosphatases differentially regulated at DTP-DTEP transition, together with the feasibility of DUSP6 targeting by small molecules, motivated us to select DUSP6 as the phosphatase to be focused in this study." (PMID 38886591, 2024). "DUSP6 expression was weak and cytoplasmic in 4/5 samples of normal breast tissue from reduction mammoplasty samples resected from patients with no known family history of breast cancer." (PMID 26859151, 2016). "In addition, the presence of DUSP6, a gene closely regulated by ERK signaling, among the top ranking genes in the molecular apocrine signature provides further support for the importance of ERK activation in this subtype of breast cancer." (PMID 22817771, 2012). "Similarly, ER+/PR+/HER2- breast cancers showed weak or absent cytoplasmic DUSP6 expression (3/10), and all (5/5) triple-negative (ER-/PR-/HER2-) breast cancers showed weak cytoplasmic DUSP6 expression." (PMID 26859151, 2016).
lung carcinoma (28 papers, 2005 to 2025). "Loss of heterozygosity of the DUSP6 locus was also found in 17.7% of lung cancer cases and was associated with reduced expression levels." (PMID 26791049, 2016). "Consistent with our findings, a frequent loss of DUSP6 expression was observed as the histological grade of the tumor increased in lung cancer." (PMID 24260056, 2013). "In addition, DUSP6 was reported to be upregulated in early lung cancer lesions with activating EGFR or RAS mutations." (PMID 41210685, 2025). "Indeed, DUSP6 downregulation has been implicated in resistance to EGFR-targeted therapy in lung cancer." (PMID 29490281, 2018). "Survival analyses available for breast and lung cancer patients supported this hypothesis as high expression of both DUSP6 and RPS6KA2 were associated with significantly improved survival in both cancer types." (PMID 28423600, 2017). "In the present study, we demonstrate that OCT4 exacerbates tumor growth and metastasis in lung cancer by transactivating DUSP6 expression." (PMID 41210685, 2025). "Collectively, these results indicate that knockdown of DUSP6 expression in OCT4-overexpressing lung cancer cells reduces tumor growth and metastasis in mice bearing A549 human lung tumor xenografts." (PMID 41210685, 2025). "ETS1/2 proteins also regulate the expression of dual specificity phosphatase 6 protein which suppresses lung cancer progression by inhibiting oncogenic ERK signaling." (PMID 37107558, 2023). "For example, DUSP6 protein expression correlates with ERK signaling activation in lung cancer cell lines, and regulation of DUSP6 is mediated at the promoter level by the ETS1 transcription factor, a well-known nuclear target of activated ERK." (PMID 34685488, 2021). "As the potential ability to dephosphorylate proteins, several DUSPs have been shown to play critical roles in human cancers, such as DUSP2 in colon cancer, DUSP6 in lung cancer, and DUSP8 in hepatocellular carcinoma." (PMID 33718185, 2021). "Using a mouse model of lung cancer, we demonstrate that the translational repression of DUSP6 by p-eIF2α is an important mechanism of mutant KRAS tumorigenesis." (PMID 34330898, 2021). "DUSP6 is functionally involved in suppressing tumor progression in pancreatic, ovarian and lung cancers." (PMID 31027181, 2019). "In transgenic mouse models of lung cancer, Dusp6 RNA was present at significantly higher levels in the lungs of mice bearing tumors driven by mutant EGFR or KRAS transgenes than in normal mouse lung epithelium." (PMID 30475204, 2018). "A survey of dual-specificity MKP expression in parental and drug resistant ELM4–ALK lung cancer cells revealed that while the parental cells had high levels of DUSP6 mRNA expression the drug resistant cells consistently had lower levels of this phosphatase." (PMID 26791049, 2016). "Overall, expression of DUSP6 gene had the strongest effect on the prediction of lung cancer based on the absolute value of the standardized coefficients (StdEst)." (PMID 27418131, 2016). "The influence of the expression of DUSP6 gene, was stronger in the older populations in terms of the odds of having lung cancer." (PMID 27418131, 2016). "The DUSP6 expression correlated inversely with the growth activity and histological grade of the tumor in lung cancer." (PMID 24260056, 2013). "NKX2-1 may control lung cancer progression through the induction of DUSP6, an ERK phosphatase, to decrease ERK activity." (PMID 35991889, 2022). "Consistent with our findings, studies of different types of solid tumors, including ovarian, breast, pancreatic, hepatocellular, esophageal, prostate, and lung carcinoma, reported that DUSP6 is under- expressed in highly proliferating tumor cells compared with normal cells." (PMID 32231719, 2020). "In lung cancer, DUSP6 is progressively lost, as tumor grade increases." (PMID 31027181, 2019).
lung carcinoma (continued). "We further delineate the EGR1 target genes in YYJD‐treated A549, including some apoptosis‐related genes such as KLF11,29, 30, 31 BCL2L1137, 38, 39, and DUSP6.40, 41 These observations suggest that the apoptosis of lung cancer cells induced by YYJD is possibly mediated by EGR1‐bound target genes." (PMID 31237749, 2019). "The loss of DUSP6 expression was secondary to loss of the transcription factor Ets1, which is known to regulate ERK-dependent DUSP6/MKP-3 transcription in both fibroblasts and lung cancer cells." (PMID 26791049, 2016). "Nonetheless, TM ETS-1 might also compete with other ETS-1-regulated tumor suppressor genes, such as DUSP6 in lung cancer." (PMID 21711453, 2011). "Additionally, DUSP6/MKP3 has been designated as a tumor suppressor phosphatase implicated in LUAD and cancer types, whereas several studies have revealed the clinical relevance of its expression patterns in lung cancer." (PMID 36551790, 2022). "In addition, five of the genes that we identified in this study, CPEB4, DUSP6, NF1, RNF4, and STAT2, were previously proposed as prognostic markers for NSCLC, whereas changes in the expression of MCM4 and WEE1 were associated with lung cancer development." (PMID 27418131, 2016). "The present study also indicated that the relative mechanisms of SLC34A2 in A549 lung cancer may be associated with the activation of the complement alternative pathway (C3 and C4b) and upregulation of the expression of SELENBP1, TXNIP, PDZK1IP1 and DUSP6." (PMID 25017204, 2014). "For example, in FGFR inhibitor-resistant lung cancer cells, NRAS amplification and DUSP6 deletion resulted in mitogen-activated protein kinase (MAPK, i.e., ERK) reactivation." (PMID 40076427, 2025). "Clinical applications of BCI in overcoming drug resistance and metastasis for the treatment of lung cancer with OCT4 and DUSP6 upregulation are warranted." (PMID 41210685, 2025). "Moreover, OCT4-induced DUSP6 upregulation may also play a role in tumor progression in lung cancer." (PMID 41210685, 2025). "This is consistent with one study on DUSP6, highlighting the importance of another DUSP enzymes in regulating ERK1/2 to prevent cell death induced by aberrant ERK1/2 activation in lung cancer." (PMID 38877005, 2024). "In human lung cancer cells, ISRIB acted in a dose-dependent manner to increase DUSP6 and decrease p-ERK in TG-treated H23 and H358 cells with KRAS G12C but not in H1299 and H1703 cells with WT KRAS." (PMID 34330898, 2021). "To analyze which is the role of DUSP6 in NSCLC, we selected the H460 cell line that belongs to this type of lung cancer." (PMID 31027181, 2019). "For each unit increase in the relative expression of the DUSP6, GRB2, and MDM2 genes, the odds of having lung cancer increased by 7.71, 7.41 and 5.36, respectively." (PMID 27418131, 2016). "The exogenous expression of DUSP6/MKP-3 has been shown to induce apoptosis by the attenuation of ERK activation in pancreatic and lung cancer." (PMID 24260056, 2013). "In the present study, we show that DUSP6 is overexpressed in human NSCLC tissues as compared to adjacent normal lung tissues and is expressed at different levels in various human lung cancer cell lines, including NSCLC cells and H661 large cell lung cancer cells." (PMID 41210685, 2025). "We also show that suppression of DUSP6 expression reverses the enhanced motility and growth of OCT4-overexpressing A549 cells both in vitro and in vivo, highlighting a new pathway for the role of OCT4 in promoting lung cancer growth and metastasis." (PMID 41210685, 2025). "Our data suggest that RA-induced changes in the expression of RARβ2, CYP26A1, CRBP1, RGS16, DUSP6, and EGR1 may be necessary for the retinoid anticancer signal in neuroblastoma, breast and/or lung cancer cells." (PMID 16012519, 2005). "Therefore, pharmacological inhibitors of DUSP6, such as BCI, as well as modulation of OCT4 and DUSP6 expression, may be further explored for treating OCT4-overexpressing lung cancer." (PMID 41210685, 2025).